LITAF (lipopolysaccharide induced TNF factor)
Description:
Plays a role in endosomal protein trafficking and in targeting proteins for lysosomal degradation. Plays a role in targeting endocytosed EGFR and ERGG3 for lysosomal degradation, and thereby helps down-regulate downstream signaling cascades. Helps recruit the ESCRT complex components TSG101, HGS and STAM to cytoplasmic membranes. Probably plays a role in regulating protein degradation via its interaction with NEDD4. May also contribute to the regulation of gene expression in the nucleus. Binds DNA (in vitro) and may play a synergistic role with STAT6 in the nucleus in regulating the expression of various cytokines. May regulate the expression of numerous cytokines, such as TNF, CCL2, CCL5, CXCL1, IL1A and IL10.
Synonyms: PIG7; SIMPLE; FLJ38636; TP53I7
Tractability: Antibody: UniProt places it where antibodies can reach, with high confidence; its Gene Ontology location is reachable by antibodies, with high confidence. PROTAC: ubiquitination databases record sites on it; its protein half-life has been measured.
Gene: Protein-coding gene on chromosome 16 (11,546,875 to 11,636,395, reverse strand). Ensembl gene ENSG00000189067.
Subcellular location: Cytoplasm; Nucleus; Lysosome membrane; Early endosome membrane; Late endosome membrane; Endosome membrane; Cell membrane; Golgi apparatus membrane
Subcellular location (Human Protein Atlas): Nucleoplasm; Golgi apparatus; Nuclear speckles; Plasma membrane; Vesicles
Gene Ontology:
Molecular function: DNA-binding transcription activator activity, RNA polymerase II-specific; identical protein binding; protein binding; RNA polymerase II cis-regulatory region sequence-specific DNA binding; WW domain binding; zinc ion binding
Biological process: positive regulation of canonical NF-kappaB signal transduction; positive regulation of transcription by RNA polymerase II; regulation of cytokine production
Cellular component: cytoplasm; cytoplasmic side of early endosome membrane; cytoplasmic side of late endosome membrane; cytoplasmic side of lysosomal membrane; cytoplasmic side of plasma membrane; early endosome membrane; endosome membrane; Golgi apparatus; Golgi membrane; late endosome membrane; lysosomal membrane; nuclear speck; nucleoplasm; nucleus; plasma membrane
Genetic constraint (gnomAD): Loss-of-function variants: 9 observed, 15.44 expected, observed/expected ratio (o/e) 0.58, 90% interval 0.35 to 1.02. The upper end of that interval is the gene's LOEUF score, 1.02, which puts it in group 4 of 6, group 1 being the genes least tolerant of losing a copy. Missense variants: 206 observed, 225.32 expected, observed/expected ratio (o/e) 0.91, 90% interval 0.81 to 1.03. Synonymous variants: 98 observed, 92.69 expected, observed/expected ratio (o/e) 1.06, 90% interval 0.9 to 1.25.
Gene-disease validity (ClinGen):
ClinGen rates the evidence that LITAF causes each of these diseases.
Charcot-Marie-Tooth disease (autosomal dominant): Moderate. An inherited degenerative disorder involving the peripheral nerves.
Homologues: Orthologues: chimpanzee LITAF (99% identical), macaque LITAF (96% identical), dog LITAF (89% identical), rat Litaf (87% identical), mouse Litaf (86% identical), guinea pig LITAF (81% identical), rabbit LITAF (71% identical), tropical clawed frog litaf (57% identical), zebrafish litaf (39% identical), Caenorhabditis elegans F16F9.1 (30% identical), Drosophila melanogaster CG13516 (24% identical), Caenorhabditis elegans Y37D8A.6 (23% identical), and 8 more. Paralogues in human: CDIP1 (34% identical).
Diseases named in the same sentence as LITAF in open-access papers:
LITAF is named in the same sentence as 55 diseases in open-access papers, as found by Europe PMC text mining. Sharing a sentence is not in itself a finding about the gene and the disease. The quoted sentences say what the papers report.
B-cell lymphoma (6 papers, 2011 to 2024). "In mature B-cell lymphoma, LITAF is inactivated by epigenetic mechanisms, but the biological functions of LITAF remain to be discovered." (PMID 27764808, 2016). "On the contrary, we characterized LITAF as a transcription factor in B-cell lymphoma, translocating to the nucleus and repressing BCL6 mRNA expression by binding to its regulatory region." (PMID 27764808, 2016). "At least in B-cell lymphoma, LPS rarely induces LITAF and the LITAF-regulated pathway in B-NHL cells might thus yield additional experiments." (PMID 27764808, 2016). "LITAF has been identified as a BCL6 target in mature B-cell lymphomas where it regulates autophagy." (PMID 26599546, 2015). "It was recently reported that autophagy is positively regulated by LITAF which is silenced by promoter hypermethylation in germinal center-derived B-cell lymphomas, suggesting that autophagy may be inhibited in these lymphomas." (PMID 25362242, 2014). "Consequently, further experiments need to be clarified whether LITAF may function as a promising target with therapeutic value in B cell lymphoma." (PMID 27764808, 2016). "Furthermore, LITAF might facilitate cell apoptosis and terminal differentiation by transcriptional repression of BCL6, thereby increasing the likelihood of other genetic events associated with the development of B-cell lymphomas." (PMID 27764808, 2016). "A recent study for the first time has demonstrated that LITAF, a novel target of BCL6, regulates autophagy in mature B-cell lymphomas." (PMID 27764808, 2016). "Surprisingly, LITAF did not induce TNF secretion upon LPS stimulation in B-cell lymphomas, and subcellular localization determined LITAF to be cytoplasmic only." (PMID 27764808, 2016). "Thus, if interaction with BCL6 enables nuclear translocation of LITAF, which subsequently represses BCL6 expression, this could explain the observed differences in subcellular localization between the two reports on B-cell lymphoma." (PMID 27764808, 2016).
endometritis (5 papers, 2023 to 2025). An acute or chronic, usually bacterial infectious process affecting the endometrium. "Using PCR-DNA sequencing for the immunological (TLR4, IL10, TLR7, NCF4, TNF-α, and LITAF) genes, there were changes in the nucleotide sequence between endometritis-affected cows and healthy ones." (PMID 37756095, 2023). "Compared to resistant cows, endometritis-affected cows produced considerably more of the genes TLR4, LITAF, TNF-α, TKT, RPIA, TLR7, TNF-α, TKT, and AMPD1." (PMID 39195794, 2024). "The expression levels of the genes TLR4, TLR7, TNF-α, NCF4, LITAF, OXSR1, TKT, RPIA, and AMPD1 were significantly greater in endometritis-affected Holstein dairy cows than in resistant ones." (PMID 37368756, 2023). "Gene expression levels were considerably higher in endometritis-affected cows than in resistant ones for the genes TLR4, TLR7, TNF-α, NCF4, LITAF, OXSR1, TKT, RPIA, and AMPD1." (PMID 37368756, 2023). "When compared to resistant cows, endometritis-affected cows had considerably higher levels of the genes TLR4, TLR7, TNF, NCF4, and LITAF expression." (PMID 37756095, 2023). "Nucleotide sequence variations between healthy and endometritis-affected cows were revealed using PCR-DNA sequencing for immune (TLR4, TLR7, TNF-α, IL10, NCF4, and LITAF), antioxidant (ATOX1, GST, and OXSR1), and erythritol-related (TKT, RPIA, and AMPD1) genes were reported by44." (PMID 38459095, 2024). "The immune (TLR4, TLR7, TNF-α, IL10, NCF4, and LITAF), antioxidant (ATOX1, GST, and OXSR1), and erythritol-related (TKT, RPIA, and AMPD1) genes in endometritis-affected and healthy Holstein dairy cows were characterized in this research using a PCR-DNA sequencing technique." (PMID 37368756, 2023). "Single nucleotide variants (SNPs) in the genes were discovered using PCR-DNA sequencing for immune (TLR4, TLR7, TNF-α, IL10, NCF4, and LITAF), antioxidant (ATOX1, GST, and OXSR1), and erythritol-related (TKT, RPIA, and AMPD1) genes found in resistant and endometritis-infected Holstein dairy cows." (PMID 37368756, 2023). "Nucleotide sequence variations between healthy and endometritis-affected cows were revealed using PCR-DNA sequencing for immune (TLR4, TLR7, TNF-α, IL10, NCF4, and LITAF), antioxidant (ATOX1, GST, and OXSR1), and erythritol-related (TKT, RPIA, and AMPD1) genes." (PMID 37368756, 2023). "Molecular genetic analyses of the immunological (TLR4, TLR7, TNF-α, IL10, NCF4, and LITAF), antioxidant (ATOX1, GST, and OXSR1), and erythritol-related (TKT, RPIA, and AMPD1) genes comparing healthy and endometritis cows found differences in nucleotide sequence and transcript levels." (PMID 37368756, 2023).
prostate carcinoma (5 papers, 2016 to 2019). A carcinoma that arises from epithelial cells of the prostate gland. "TCGA dataset analysis revealed that LITAF was significantly downregulated in prostate cancer compared to matched normal samples (P = 0.02, two‐sided Wilcoxon test)." (PMID 29845714, 2018). "This also highlights a novel role for LITAF in prostate cancer radioresistance and disease progression." (PMID 29845714, 2018). "In this study, we describe for the first time two novel players in prostate cancer radioresistance: miR‐106a and LITAF." (PMID 29845714, 2018). "We performed bioinformatics analyses of The Cancer Genome Atlas (TCGA) dataset to evaluate the association between miR‐106a and its putative target lipopolysaccharide‐induced TNF‐α factor (LITAF) in prostate cancer." (PMID 29845714, 2018). "This suggests that LITAF downregulation, likely by miR‐106a, is involved in prostate cancer tumorigenesis and tumor progression." (PMID 29845714, 2018). "Third, we have previously shown that knockdown of LITAF promotes proliferation and migration of prostate cancer cells." (PMID 26717043, 2016). "The expression of LITAF in prostate cancer cells is upregulated by activation of AMPK and suppressed by a dominant negative mutant of AMPKα1 subunit or its shRNA." (PMID 26717043, 2016). "TNFSF15 inhibits the growth of prostate cancer cells and bovine aortic endothelial cells in vitro, supporting that LITAF may function as a tumor suppressor." (PMID 30871256, 2019). "To identify whether LITAF is involved in radioresistant prostate cancer, we evaluated whether LITAF expression may also be perturbed in PC3 IRR cells compared to parental." (PMID 29845714, 2018). "Recent studies have shown that LITAF is frequently down-regulated in different types of cancer, including acute leukemia, breast cancer, lymphoma, and prostatic cancer, suggesting that it may function as a tumor suppressor gene." (PMID 29423035, 2018). "Furthermore, silencing of LITAF in prostate cancer cells promotes proliferation, anchorage-independent growth, and xenograft tumor development." (PMID 26717043, 2016). "Besides that, LITAF inhibits cell proliferation by specially binding to the same consensus motif, CTCCC (−515 to −511), and activating transcription of TNFSF15 in prostate cancer." (PMID 27764808, 2016). "Our findings identify miR‐106a and LITAF as novel modulators of radioresistance through ATM upregulation and suggest that miR‐106a may be a promising biomarker for high‐grade disease and radioresistant prostate cancer." (PMID 29845714, 2018).
Salmonella Infections (5 papers, 2019 to 2025). Infections with bacteria of the genus SALMONELLA. "Many studies have indicated that the expression of proinflammatory cytokines such as IFN-γ, IL-6, IL-1β, LITAF, and anti-inflammatory cytokines (IL-10 and transforming growth factor-β4) is regulated in the cecal tonsils by Salmonella infection." (PMID 32054193, 2020). "Salmonella infection can lead to mild intestinal inflammation, which releases cytokines and other factors like interleukin-6 (IL-6), IL-8, IL-12, LPS-induced tumor necrosis factor alpha (LITAF) and interferon gamma (IFN-γ)." (PMID 36311708, 2022). "Both wild-type and knockout chickens showed significant upregulation of pro-inflammatory cytokines after Salmonella infection, including IFN-γ, IL-1β, IL-22, LITAF, and the chemokine K203, compared to their mock-infected controls." (PMID 40438105, 2025).
viral infection (5 papers, 2013 to 2023). "Further, LITAF is involved in the immune response against bacterial and viral infections and can regulate TNF-α transcription, inflammation, proliferation, and apoptosis." (PMID 36140805, 2022). "SCRaV encodes homologs of LITAF, TNFR, and apoptosis regulator (61L, 72L, 41L, and 70L), which could have functions in the regulation of cell death and inflammation and prompt virus infection, as reported in other ranaviruses." (PMID 37242400, 2023). "Considering that miRNA act as rheostats to modulate the output of gene expression, one reasonable explanation for the paradox is that miR-homoHSV may inhibit aberrantly transcribed SGIV LITAF mRNA in the process of viral infection to facilitate a complete viral life cycle." (PMID 24312676, 2013). "Duck cells treated with S3I-201 that inhibits the transcriptional activity of STAT-3, resulted in increased expression of LITAF, IL-6 and IL-8 compared with control cells at 24 h post H5N1-tyEng91 virus infection." (PMID 25431115, 2014). "Meanwhile, miR-homoHSV expression was able to attenuate cell death induced by viral infection, presumably facilitating viral replication through the down-regulation of the pro-apoptotic gene SGIV LITAF." (PMID 24312676, 2013). "Additionally, compared to control fish, viral infection led to changes in host cell transcription of several inflammatory cytokines, including TNFα, IL1, LITAF, TLR18, and NFκB." (PMID 34185811, 2021).
Charcot-Marie-Tooth disease (4 papers, 2012 to 2018). "Apart from its critical role in inflammatory response, mutations in LITAF are associated with Paget's disease and Charcot-Marie-Tooth disease (CMT)." (PMID 27764808, 2016). "Mutations in LITAF have been identified in Charcot-Marie tooth disease, a disease characterized by protein aggregates." (PMID 22276139, 2012). "Mutations in lipopolysaccharide-induced tumor necrosis factor-alpha factor (LITAF)/SIMPLE, that interacts with HGS and STAM1 in the ESCRT-0 complex, cause a demyelinating form of Charcot Marie Tooth disease, suggesting that ESCRT-0 is required for myelin formation or stability." (PMID 26115514, 2015).
glioma (4 papers, 2022 to 2025). A benign or malignant brain and spinal cord tumor that arises from glial cells (astrocytes, oligodendrocytes, ependymal cells). "Recently, a study demonstrated that the LITAF expression is decreased in glioma tissues, which likely enhances the radiosensitivity of glioma cells through upregulating the FoxO1 pathway." (PMID 35429411, 2022). "The transcription factor LITAF promotes radiosensitivity in gliomas." (PMID 40507925, 2025). "Comparative analysis demonstrated elevated LITAF, OSMR, and TCF12 expression in glioma versus normal tissues at transcriptional level." (PMID 40859405, 2025).
lymphoma (4 papers, 2014 to 2021). A malignant (clonal) proliferation of B- lymphocytes or T- lymphocytes which involves the lymph nodes, bone marrow and/or extranodal sites. "In line with this, recent studies have documented that expression of LITAF promotes apoptosis and differentiation of acute myeloid leukemia cells and that autophagy is suppressed in lymphoma cells where LITAF was silenced by BCL6." (PMID 26717043, 2016). "This work does not clearly delineate whether silencing of LITAF in these lymphomas is a coincident or cause-effect event." (PMID 26717043, 2016). "Also, in BCL6-driven lymphomas, inhibition of autophagy through BCL6-mediated transcriptional repression of LITAF (lipopolysaccharide (LPS)-induced TNF alpha (TNFα) factor) has been proposed to be implicated in their pathogenesis." (PMID 34782660, 2021).
Charcot-Marie-Tooth disease type 1C (3 papers, 2016 to 2021). Any Charcot-Marie-Tooth disease type 1 in which the cause of the disease is a mutation in the LITAF gene. "Mutations in LITAF give rise to the peripheral neuropathy, Charcot Marie Tooth disease type 1C (CMT1C)." (PMID 34342350, 2021). "Mutations in Lipopolysaccharide-induced tumour necrosis factor-α factor (LITAF) cause the autosomal dominant inherited peripheral neuropathy, Charcot-Marie-Tooth disease type 1C (CMT1C)." (PMID 27927196, 2016). "Charcot-Marie-Tooth disease type 1C (CMT1C) is a rare form of CMT1 caused by mutations in the lipopolysaccharide-induced tumor necrosis factor (LITAF) or small integral membrane protein of the lysosome/late endosome (SIMPLE) gene." (PMID 32665875, 2020).
demyelinating peripheral neuropathy (2 papers, 2020 to 2024). "Autosomal dominant mutations in LITAF are responsible for the rare demyelinating peripheral neuropathy, Charcot–Marie–Tooth disease type 1C (CMT1C)." (PMID 33059769, 2020). "Indeed, in regard to CMT diseases, it was also shown that mutations in the LITAF/SIMPLE gene encoding LPS-Induced TNF-Alpha Factor (LITAF) are linked to CMT1C, a demyelinating peripheral neuropathy." (PMID 39795872, 2024).
leukemia (2 papers, 2016 to 2020). A malignant (clonal) hematologic disorder, involving hematopoietic stem cells and characterized by the presence of primitive or atypical myeloid or lymphoid cells in the bone marrow and the blood. "The lipopolysaccharide-induced TNF factor (LITAF) has been suggested to sensitize leukemia cells to chemotherapeutic drugs, especially in cells with a lower expression of LITAF60." (PMID 32029838, 2020).
neuroblastoma (2 papers, 2015 to 2017). Neuroblastoma (NB) is the most common solid, extracranial childhood tumor. "In neuroblastoma cell lines expressing WT and mutant forms of LITAF, CMT-causing LITAF mutants are mislocalised to the mitochondria, while the WT form traffics through the secretory pathway to the late endosome/lysosome." (PMID 28553203, 2017). "Despite this difference in procedure, we see changes in nucleosome positioning in EGR1, LITAF, MLL3 and possibly DHFR, beginning at the 10 minute time point that are consistent with transcriptional changes following one hour nicotine exposure in the SH-SY5Y neuroblastoma cell line." (PMID 26414157, 2015).
Burkitt lymphoma (1 paper, 2016). A rare form of malignant mature B-cell non-Hodgkin lymphoma. "In addition, the expression of LITAF and BCL6 was assayed in six B-NHL cell lines including Burkitt's lymphoma cell lines (Raji, Daudi, Ramos and Namalwa) and DLBCL cell lines (OCI-Ly3 and OCI-Ly6) at mRNA and protein level." (PMID 27764808, 2016).
cardiac arrhythmia (1 paper, 2018). Any disturbances of the normal rhythmic beating of the heart or MYOCARDIAL CONTRACTION. "To illustrate this point, we highlight two genes: TBX5, a gene directly linked to cardiac arrhythmia, and LITAF, a gene that, until recently, had no obvious role in cardiac biology." (PMID 29988018, 2018).
co-infection (1 paper, 2023). "and C. perfringens co-infection was highly correlated with IFN-α, IFN-γ, IL-4, IL-13, IL-16, LITAF, TGF-β4 and TNFSF15 in the jejunum, indicating that Th2 type cytokines mainly participated in avian NE." (PMID 37240767, 2023).
colon cancer (1 paper, 2015).
colonic inflammation (1 paper, 2011). "To determine whether LITAF participates in the mediation of TNF-α expression in acutely inflamed colonic tissues, we first established the TNBS-induced colonic inflammation model in C57BL/6 mice." (PMID 21984950, 2011).